PIK3CA (phosphatidylinositol-4,5-bisphosphate 3-kinase catalytic subunit alpha)
Diseases named in the same sentence as PIK3CA in open-access papers (continued):
Sharing a sentence is not in itself a finding about the gene and the disease.
tumor (continued). "A discordance between primary tumours and distant metastases was observed for KRAS in 10% of the cases and for PIK3CA in 5% of the cases." (PMID 21139621, 2010). "In contrast, knock-down of BRAF+CRAF, BRAF+PIK3CA, and MEK1/2+PIK3CA in IPC298 cells led to accumulation of cells in S or G1-phase consistent with the adverse effect on tumor growth observed in vivo." (PMID 19492075, 2009). "Importantly, patients whose tumour had BRAF or PIK3CA mutation had shorter PFS regardless of whether cetuximab was administered in the second, or third and higher lines (interaction tests P=0.5 and 0.6, respectively)." (PMID 19603024, 2009). "In in vivo tumor growth studies, tumors carrying shRNAs that target NRAS alone, or combinations of BRAF and CRAF, or BRAF and PIK3CA, showed a significant delay in tumor growth compared to the corresponding sucrose controls." (PMID 19492075, 2009). "In contrast to knock-down of PIK3CA in HCT116, nude mice bearing subcutaneous tumors resulting from injected HCT116 BRAF-inducible shRNAs cells, when treated with dox showed a delay in tumor growth." (PMID 19492075, 2009). "Furthermore, it remains unclear how such roles of PIK3CA might be affected by the tumor milieu." (PMID 18335034, 2008). "A total of 280 HNSCC tumours from 280 patients were analysed by FISH for copy number changes of proto-oncogenes CCNL1, SNO PIK3CA and TP73L located on chromosomal band 3q25–q29." (PMID 15700036, 2005). "Furthermore, the identification of oncogenes such as KRAS, MYC, and PIK3CA as being more effective targets than tumor suppressor genes (effect size: 0.87 vs 0.79, P = .03) suggested that oncogene knockout could be a more potent strategy for tumor growth control." (PMID 41517680, 2026). "Even when using PIK3CA inhibitors (such as alpelisib) to inhibit PI3K/AKT, tumor cells may continue to proliferate by activating other pathways such as MAPK or JAK/STAT." (PMID 39911393, 2025). "Furthermore, the reduction in oncogene expression (e.g., PIK3CA and CCDN1) highlights the effectiveness of the FEO-CSNPs in suppressing tumor growth-related gene activity." (PMID 40284420, 2025). "Furthermore, eFT226 synergises with PIK3CA inhibitor alpelisib and Akt inhibitor ipatasertib to induce cytotoxicity in RTK-driven tumours in vitro and in vivo." (PMID 40805230, 2025). "Importantly, PIK3CA mutations were significantly associated with disease progression and shorter PFS, but this effect was not retained after multivariate adjustment, suggesting that their prognostic impact may be confounded by tumor subtype and related prognostic covariates." (PMID 41415546, 2025). "This further suggests that PI3K pathway alterations are a frequent molecular event in TNBC and that the respective contributions of RICTOR, PIK3CA, and PTEN to mTOR hyperactivation may drive tumor progression." (PMID 40019775, 2025). "Of the 5 HPV-associated SNSCC with PIK3CA missense mutations 3 tumors had E542K and 1 tumor had E545K mutations (4/5, 80%), while no HPV-independent SNSCC demonstrated PIK3CA hotspot mutations." (PMID 40500270, 2025). "Together, we demonstrated that the combination of alpelisib + OT is tolerable in a NSG mice xenograft RMS PDXs, significantly decreased PIK3CA/AKT pathway activity and p-NRF2, and ultimately inhibited MDR mechanisms to decreased tumor volume and subsequently prolonged survival." (PMID 41372143, 2025).
tumor (continued). "Stratified Fisher’s exact tests confirmed that the lower mutation frequencies in TA-UC (PIK3CA, combined P = 0.008; PIK3R1, combined P = 0.001) were not driven by the different distributions of tumor grades in our TA-UC and de novo UC cohorts." (PMID 40846762, 2025). "Similarly, a clinical trial with PI3K inhibitor copanlisib in PIK3CA- and ARID1A-mutant cancers demonstrated a significant decrease in tumor growth." (PMID 41514650, 2025). "Combining fulvestrant (an Estrogen Receptor (ER) degrader) with the PI3K-AKT signalling inhibitors alpelisib (PI3Kαi) or capivasertib (AKTi) provides benefit in ER+ breast cancer (BC) patients with PIK3CA altered and PIK3CA, PTEN and AKT-1 altered tumours respectively." (PMID 40263319, 2025). "Our observations indicate that medicarpin may inhibit these processes by targeting both upstream and downstream components, including PIK3CA, AKT1, and mTOR, therefore resensitizing tumor cells to apoptotic signals." (PMID 41516052, 2025). "For example, RVdriver fails to identify PIK3CA as a putative cancer gene in thirteen tumor types in which it is identified by DNA approaches, and only successfully identifies it as such in three cancer types." (PMID 40514689, 2025). "Interestingly, PIK3CA/AKT pathway inhibitors robustly killed resistant tumors in the presence of OT and yet had only moderate impact on tumor cell killing in the parental, therapy-sensitive cells." (PMID 41372143, 2025). "This also aligned with evidence suggesting that PiK3ca mutations, present in LLC and KP but not in CMT cells, are encountered preferentially in advanced‐stage tumours." (PMID 40530801, 2025). "This was reinforced by FA ratios revealing that arachidonic acid metabolism was more prevalent in PIK3CA-stratified, but not receptor-stratified tissues, even though all tumor tissues exhibited increased overall FA(18:2) metabolism." (PMID 39294437, 2024). "Results were presented for the ITT population and for a subgroup of patients with genetic alterations in tumor tissue of PIK3CA, PTEN, and AKT1 (the latter will not be presented here)." (PMID 39742383, 2024). "Moreover, the location of the primary tumor can be determined with high accuracy (71%), while TEP mRNA profiles can be useful to highlight HER2-positive, PIK3CA, and triple-negative BC tumors." (PMID 39274207, 2024). "In the Inserm cohort, PIK3CA oncogenic alterations were detected in 55 (38.5%) HR+/HER2- tumours, 6 (11.8%) TNBC, 3 (21.4%) HER2-enriched lesions, four tumours with unknown subtype." (PMID 39322687, 2024). "Molecularly, GBM06 was the only tumor with MGMT promoter methylation and a PIK3CA I391M mutation, which does not alter kinase activity, but eventually increases cell proliferation and viability." (PMID 39054369, 2024). "No statistical differences in the distribution of other clinicopathological variables such as age, histologic grade, tumor size, and HER2 status were observed between primary tumors with vs without PIK3CA mutation." (PMID 38822093, 2024). "As with human CRCs, the drug combination induced tumor regression and apoptosis of PIK3CA mutant, but not parental, CMT93 tumors." (PMID 38194275, 2024). "The use of the MEK inhibitor alone, or PIK3CA inhibitor alone, did not provide a favorable response to this type of tumor." (PMID 39056802, 2024). "AKT transcript overexpression is frequently observed, and is associated with tumor grade and aggressiveness, irrespective of AKT phosphorylation, in both PIK3CA-mutated and PIK3CA-wild-type tumors." (PMID 38954770, 2024).
tumor (continued). "In the PIK3CA/PTEN mutant model (PDX361836), gedatolisib, alpelisib, and everolimus induced significant tumor cell growth inhibition (TCGI) relative to vehicle (85%, 55%, 60% with p = 0.001, p = 0.043, p = 0.014, respectively), while capivasertib induced modest, non-significant TCGI (20%, p = 0.35)." (PMID 38839777, 2024). "However, capivasertib can deliver monotherapy and combination activity beyond tumours with alterations in PTEN, PIK3CA or AKT1." (PMID 39284898, 2024). "Additionally, miR-10a enhances the resistance of circulating tumor cells (CTCs) to cisplatin and inhibits the PI3K/Akt pathway by targeting PIK3CA, providing a novel therapeutic target for NSCLC treatment." (PMID 38655260, 2024). "A somatic PIK3CA:c.3140A>G:p.H1047R mutation with a high allele frequency in our WES analysis (0.9), identified through whole-exome sequencing of the tumor and absent in genomic DNA, was selected as a marker for early recurrence monitoring." (PMID 39596073, 2024). "Nine variants reported in the tumor tissue across EGFR, KRAS, BRAF, and PIK3CA were not covered by the UltraSEEK® Lung Panel." (PMID 37686200, 2023). "Engineered Mut PIK3CA–specific TCR-T cells showed an antitumor response against established tumors in vivo in mice bearing PIK3CA-Mut tumor but not wild-type PIK3CA tumors." (PMID 36791198, 2023). "Retrospective analysis of archival tumor specimens and droplet-digital PCR-based liquid biopsy from BOLERO-2 showed that the presence of PIK3CA mutation was a prognostic but not predictive biomarker." (PMID 37344660, 2023). "ENTPD1, IL17A, and P2RX7 were downregulated, while HSP90AA1, PIK3CA, and NT5E were upregulated, indicating that ENTPD1, IL17A, and P2RX7 might negatively affect tumor development and result in better outcome." (PMID 37587188, 2023). "Also, in a wide variety of neoplasms, PIK3C genes appear amplified, whereas in prostate cancer, the PIK3CA gene is overexpressed." (PMID 37509254, 2023). "IGROV-1 is derived from a mixed histology tumor and contains mutant ARID1A and PIK3CA and could be considered a clear cell-like line." (PMID 37621654, 2023). "Tumor types carrying PTEN mutation, PIK3CA mutation, or HER2 amplification, without coincident RAS mutation, are strongly associated with preclinical sensitivity to capivasertib." (PMID 36765661, 2023). "Increased PIK3CA alterations and downregulation of SCGB2A1, the inhibitor of PI3K kinase, in hDNAmad+ tumors, might promote tumor growth/proliferation and stemness." (PMID 37388735, 2023).
tumor (continued). "Whereas none of the samples presented with a PIK3CA E542 mutation, MBC-PDO #05 and MBC-PDO #06 had an E545 hotspot mutation that was also present in the primary tumor of the corresponding patients." (PMID 37509265, 2023). "PDX models developed represented similar genomic (e.g., ARID1A, PIK3CA, KRAS etc.)and protein (PAX8, ARID1A, napsin A, racemase) profiles to the native patient tumor from which they were derived supporting use of these models as surrogates of the patient tumor." (PMID 37841875, 2023). "For the BRAF, PIK3CA, and SMAD4 genes, no eligible studies were found that investigated the role of genetic tumor mutations on tumor downstaging." (PMID 36900260, 2023). "In the expanded testing panel that used advances in genetic testing assays, PIK3CA, AKT1 and PTEN alterations were identified in tumours from 76 (54%) of the 140 participants in the intention-to-treat population (39 who received capivasertib and 37 who received placebo)." (PMID 35671774, 2022). "Also, PIK3CA overtook MYC as the top CNA-based oncogene, and PTEN displaced CDKN2A from the top CNA-based tumour suppressor spot." (PMID 35975235, 2022). "Because tumor variations may be a factor for survival, we included KRAS and PIK3CA variation status in 461 patients with available data." (PMID 36239938, 2022). "The comparison of whole-genome sequencing and whole-exome sequencing analyzes of Asian and Caucasian patients shows that there are substantial differences in the molecular tumor characteristics such as the alteration rate of important driver genes such as APC, ARID1A, PTEN and PIK3CA." (PMID 35326507, 2022). "It was shown that tumors with high PIK3CA CN have more aggressive prognostic features, including large tumor size, high tumor grade, and negative HR status and are more likely to occur in patients with HR and HER2 negative disease." (PMID 35181669, 2022). "The ORr was 29% among patients with PIK3CA alterations compared to no objective tumor response in the PI3KCA wild-type group." (PMID 35565291, 2022). "Partial or complete response was observed among 29% of pretreated metastatic breast cancer patients with PIK3CA alterations, whereas no tumor response was reported in the PIK3CA wild-type group." (PMID 34298731, 2021).
tumor (continued). "Interestingly, the result suggested a downregulation of PIK3CA mRNA levels in KIRC patients compared to normal controls in subgroup analyses based on race, gender, age, KIRC subtypes, tumor grade, cancer stages, and nodal metastasis status." (PMID 34367282, 2021). "The tumor sample from the pazopanib plus everolimus‐responsive patient had a PIK3CA A1035V alteration not known to be activating." (PMID 34269527, 2021). "In order to better understand the effects of mutant PIK3CA on response and resistance to different types of therapies, the same tumor should be treated with different agents, which is not possible in the clinic." (PMID 33886505, 2021). "There were similar mutational landscapes in MMRd tumours regardless of aetiology, although co-occurring mutations in PTEN, PIK3CA and KRAS were more common in sporadic MMRd and perturbations of TGF-β signalling more common in LS-EC." (PMID 34572765, 2021). "In vitro experiments showed that FSCN1 silencing sensitized tumor cells with PIK3CA alterations, but not cells with wild-type PIK3CA to IR." (PMID 34249689, 2021). "Our study shows that FSCN1 silencing can increase the radiation sensitivity of tumor cells with PIK3CA alterations but not in cells with wild-type PIK3CA." (PMID 34249689, 2021). "All of the selected patients had the phosphatidylinositol-4,5-bisphosphate 3-kinase catalytic subunit alpha (PIK3CA) activator mutation, but no tumor response was recorded." (PMID 34513491, 2021). "Subcutaneous injections of HMOsisEC10 KRAS and HMOsisEC10 PIK3CA mutant cells in nude mice did not produce any forms of tumor within two months of monitoring." (PMID 34202354, 2021). "Finally, it is important to note that, although a KD might be beneficial for certain established tumour phenotypes (e.g., PIK3CA-mutated tumours), this approach might not be effective—and could potentially be detrimenta—in certain other tumour types and in the preventive setting." (PMID 33911195, 2021). "In the same study, an alectinib-resistant tumor specimen showed no ALK resistance mutation; however, a PIK3CA G106V mutation was found in this tumor." (PMID 33572278, 2021). "PI3K pathway inhibitors did not decrease tumor growth in the two AKT1-mutated models, but HBCx-2 PDX responded to the mTOR inhibitor AZD2014 (TGI=86%, p=0.0001) and the dual inhibitor (mTOR and PIK3Ca) (TGI =70%, p=0.001)." (PMID 32042320, 2020). "Improvement in PFS was maintained using everolimus, irrespective of PIK3CA genotypes (detected by ctDNA), and it was consistent withprevious analysis of archival tumor DNA using NGS." (PMID 32010431, 2020). "Our results show that the efficacy of combination treatment was not dependent on PIK3CA tumor status." (PMID 32825725, 2020). "In addition, copy number gain of PIK3CA was present in all samples, as well of AKT1 in TC1 and TC4 PDX tumours." (PMID 33144587, 2020).